PPP1R2 (protein phosphatase 1 regulatory inhibitor subunit 2)
Description:
Inhibitor of protein-phosphatase 1.
Synonyms: IPP-2; IPP2; PPP1R2A
Tractability: PROTAC: ubiquitination databases record sites on it; its protein half-life has been measured.
Gene: Protein-coding gene on chromosome 3 (195,514,428 to 195,543,386, reverse strand). Ensembl gene ENSG00000184203.
Subcellular location (Human Protein Atlas): Nucleoplasm; Cytosol
Gene Ontology:
Molecular function: molecular function inhibitor activity; protein binding; protein serine/threonine phosphatase inhibitor activity; protein phosphatase inhibitor activity
Biological process: generation of precursor metabolites and energy; intracellular signal transduction; regulation of signal transduction
Genetic constraint (gnomAD): Loss-of-function variants: 14 observed, 20.05 expected, observed/expected ratio (o/e) 0.7, 90% interval 0.46 to 1.09. The upper end of that interval is the gene's LOEUF score, 1.09, which puts it in group 4 of 6, group 1 being the genes least tolerant of losing a copy. Missense variants: 154 observed, 194.58 expected, observed/expected ratio (o/e) 0.79, 90% interval 0.69 to 0.9. Synonymous variants: 65 observed, 71.07 expected, observed/expected ratio (o/e) 0.91, 90% interval 0.75 to 1.12.
Homologues: Orthologues: chimpanzee PPP1R2 (99% identical), macaque PPP1R2 (99% identical), rabbit PPP1R2 (92% identical), rat Ppp1r2 (85% identical), mouse Ppp1r2 (84% identical), dog PPP1R2 (83% identical), mouse Ppp1r2-ps5 (82% identical), mouse Ppp1r2-ps1 (82% identical), mouse Ppp1r2-ps6 (82% identical), zebrafish ppp1r2 (57% identical), tropical clawed frog ppp1r2 (49% identical). Paralogues in human: PPP1R2B (96% identical), PPP1R2C (42% identical).
Diseases named in the same sentence as PPP1R2 in open-access papers:
PPP1R2 is named in the same sentence as 18 diseases in open-access papers, as found by Europe PMC text mining. Sharing a sentence is not in itself a finding about the gene and the disease. The quoted sentences say what the papers report.
Diabetes (2 papers, 2023 to 2024). "For instance, TXNDC5’s interactions with NENF, PPP1R2, ALDOC, LDH, or PGD may help explain its relevance in diabetes." (PMID 38138960, 2023).
bladder cancer (1 paper, 2025). "Higher whole blood expression of FAM53A and PPP1R2 was associated with higher odds of bladder cancer, while higher expression of SLC39A3 and ZNF737 was associated with lower odds of bladder cancer." (PMID 39789109, 2025). "A total of four genes (SLC39A3 on 19p13.3, ZNF737 on 19p12, FAM53A on 4p16.3, and PPP1R2 on 3q29) were identified to be associated with bladder cancer risk with FDR < 0.05." (PMID 39789109, 2025). "Our TWAS also suggests that higher circulating PPP1R2 expression is associated with higher bladder cancer risk." (PMID 39789109, 2025). "TWAS identified four genes for which expression levels were associated with bladder cancer risk: SLC39A3 (OR = 0.91, CI = 0.87–0.95, FDR = 0.015), ZNF737 (OR = 0.91, CI = 0.88–0.95, FDR = 0.016), FAM53A (OR = 1.09, CI = 1.05–1.14, FDR = 0.022), and PPP1R2 (OR = 1.09, CI = 1.05–1.13, FDR = 0.049)." (PMID 39789109, 2025). "We did not identify any GWAS-identified bladder cancer risk SNPs located within 1 Mb of SLC39A3, ZNF737, and PPP1R2." (PMID 39789109, 2025). "Studies of the role of PPP1R2 in bladder cancer specifically, however, are lacking." (PMID 39789109, 2025).
pancreatic cancer (1 paper, 2026). "We next directly examined the roles of LZTR1 and PPP1R2/PP1C in regulating KRAS stability across the tested adenocarcinoma lines, as well as in the pancreatic cancer line Mia PaCa-2." (PMID 41542462, 2026).
tumor (5 papers, 2015 to 2025). "Contrary to the serum profile, urine from OH-BBN induced C57BL/6 mice displayed increased levels of the pro-inflammatory cytokines Ccl3 and Il1β, as well as an upregulation of tumor promoting Ppp1r2, Pak4, tumor growth marker Nadk, and Dctn2." (PMID 34232958, 2021).
adenocarcinoma (1 paper, 2026). A common cancer characterized by the presence of malignant glandular cells. "Together, these data suggest that RAS stability is differentially regulated in hematologic cancers versus adenocarcinomas and further support the notion that PPP1R2/PP1C/LZTR1-dependent regulation of KRAS stability is a feature of hematologic cancers." (PMID 41542462, 2026).
PPP1R2 also shares sentences with these, for which no sentence is quoted: cancer (3 papers); schizophrenia (2); abdominal aortic aneurysm (1); aneurysm (1); Anxiety (1); breast carcinoma (1); glioma (1); hematologic cancers (1); hematologic malignancies (1); hepatocellular carcinoma (1); hypotrichosis simplex (1); Neurological Disorder (1); polycythemia (1).